BCL11B (BCL11 transcription factor B)
Diseases named in the same sentence as BCL11B in open-access papers (continued):
Sharing a sentence is not in itself a finding about the gene and the disease.
Ewing sarcoma (12 papers, 2013 to 2025). A small round cell tumor that lacks morphologic, immunohistochemical, and electron microscopic evidence of neuroectodermal differentiation. "To offer a simple, fast, and cost-effective way to reliably diagnose Ewing sarcoma by IHC, we combined in silico, in vitro, and in situ analyses, and found that the high expression of BCL11B and/or GLG1 is nearly diagnostic for this disease." (PMID 29416716, 2018). "We next took a loss of function approach to determine the involvement of BCL11B in maintenance of transformation in Ewing sarcoma." (PMID 23527175, 2013). "Expression of HEY1, HES1, and BCL11B was also increased in human mesenchymal chondrosarcoma compared with other sarcomas such as myxoid liposarcoma, Ewing sarcoma, osteosarcoma, and synovial sarcoma." (PMID 37212282, 2023). "Collectively, our data provide evidence that fast and robust diagnosis of Ewing sarcoma is enabled by immunohistochemical detection of the super-enhancer-driven EWSR1-ETS targets BCL11B and GLG1." (PMID 29416716, 2018). "Although most Ewing sarcoma tumors show only little infiltration by lymphocytes, the fact that BCL11B is expressed in normal T cells should be taken into account when assessing immunoreactivity in small-round-cell tumors." (PMID 29416716, 2018). "In fact, our three markers, except for BCL11B in thymus, were statistically significantly higher (P < 0.05) expressed in Ewing sarcoma as compared to any tested normal tissue type." (PMID 29416716, 2018). "Since high expression of BCL11B and/or GLG1 (defined as IRS > 9) was found in 79% of all Ewing Sarcoma cases and associated with a specificity of 96%, diagnosis of Ewing sarcoma should be strongly considered if one or both markers are highly expressed." (PMID 29416716, 2018). "Collectively, we propose utilizing BCL11B and GLG1 as novel biomarkers for the diagnosis of Ewing sarcoma and recommend validating their diagnostic value in a prospective and multi-centered setting." (PMID 29416716, 2018). "To explore the potential of ATP1A1, BCL11B, GLG1, and CD99 as prognostic biomarkers, we analyzed the association of their expression levels with outcome in a large cohort of Ewing sarcoma patients (n = 166)." (PMID 29416716, 2018). "This EWS/FLI-dependent up-regulation of BCL11B is necessary for the maintenance of the transformed phenotype in Ewing sarcoma cell lines in vitro." (PMID 23527175, 2013). "As BCL11B is a transcription factor, we sought to identify the genes it regulates in Ewing sarcoma to gain insight into its function in sustaining tumorigenicity." (PMID 23527175, 2013). "This further implicates BCL11B mediated repression as an important contributor to the repressed gene signature in Ewing sarcoma cells." (PMID 23527175, 2013). "BCL11B was identified as a gene that was highly expressed in Ewing sarcoma, but only expressed in a restricted subset of normal tissues." (PMID 23527175, 2013). "We further demonstrate that re-expression of SPRY1, a repressed target of BCL11B, limits the transformation capacity of Ewing sarcoma cells." (PMID 23527175, 2013). "Ewing sarcoma cells with reduced BCL11B expression grew in tissue culture with a slightly reduced growth rate." (PMID 23527175, 2013). "BCL11B is highly expressed in Ewing sarcoma cell lines and tumor samples and has been identified as an EWS/FLI up-regulated target in numerous microarray studies." (PMID 23527175, 2013). "This allows for the possibility that in the likely primitive Ewing sarcoma cell of origin, the BCL11B promoter has an open chromatin structure that permits the strong activation of BCL11B following the formation of the translocation." (PMID 23527175, 2013). "Here we characterize BCL11B as an up-regulated EWS/FLI target that is necessary for the maintenance of transformation in patient derived Ewing sarcoma cells lines." (PMID 23527175, 2013).
Ewing sarcoma (continued). "BCL11B, a zinc finger transcription factor, acts as a transcriptional repressor in Ewing’s sarcoma and contributes to the EWS/FLI repressed gene signature." (PMID 23527175, 2013). "Even at these lower concentrations, it significantly reduced the expression of BCL11B, and so prevented us from drawing any conclusions about the involvement of SUV39H1 in BCL11B mediated repression in Ewing sarcoma." (PMID 23527175, 2013). "Using a knock-down/rescue approach in two different Ewing sarcoma cell lines (A673 and TC71), we found that reduction of EWS/FLI levels via a retroviral shRNA causes a significant reduction in BCL11B RNA and protein expression levels." (PMID 23527175, 2013). "Here we have shown the aberrant expression of BCL11B in Ewing sarcoma cell lines represses a subset of the EWS/FLI repressed gene signature and contributes to the transformed phenotype." (PMID 23527175, 2013). "We therefore sought to define the role of BCL11B in Ewing sarcoma." (PMID 23527175, 2013). "We tested the necessity of these three co-repressors in BCL11B-mediated repression in Ewing sarcoma cells by shRNA knock-down for chomodomain helicase DNA binding protein 4 (CHD4), the core component of the NuRD complex, or chemical inhibitors targeting SUV39H1 or SIRT1." (PMID 23527175, 2013). "We have shown that EWS/FLI is responsible for the expression of BCL11B in Ewing sarcoma cells." (PMID 23527175, 2013). "BCL11B expression in Ewing sarcoma has been noted previously." (PMID 23527175, 2013). "Our data suggests that BCL11B contributes to the overall EWS/FLI repressed gene signature in Ewing sarcoma, and that the repression of a subset of these genes may be necessary for the transformed phenotype." (PMID 23527175, 2013). "Moreover, BCL11B was shown to be upregulated by EWSR1-FLI1 in Ewing sarcoma cell lines." (PMID 29416716, 2018). "Some of these transcription factors, such as NR0B1 or BCL11B, have been previously shown to be regulated by EWSR1-FLI1 and play important functional roles in Ewing sarcoma pathogenesis." (PMID 34830820, 2021). "This approach generated a total of 147 genes, containing a number of known Ewing sarcoma oncogenes such as CCND1, NKX2–2, BCL11B and MYC." (PMID 30496486, 2019). "In fact, detecting high BCL11B and/or GLG1 expression in CD99-high tumors reached a specificity for Ewing sarcoma of at least 96%, and of 99% if both markers were highly expressed (defined as IRS > 9)." (PMID 29416716, 2018). "While CD99 showed broad expression in many different tumor entities, ATP1A1, BCL11B, and GLG1 were only expressed at low levels in every tumor entity relative to Ewing sarcoma, indicating a higher specificity for this disease than CD99." (PMID 29416716, 2018). "Automated cut-off-finding and combination-testing in a tissue-microarray comprising 174 samples demonstrated that detection of high BCL11B and/or GLG1 expression is sufficient to reach 96% specificity for Ewing sarcoma." (PMID 29416716, 2018). "In the current study, comparative expression analyses revealed that ATP1A1, BCL11B, and GLG1 constitute potential specific markers for Ewing sarcoma." (PMID 29416716, 2018). "Collectively, we show that ATP1A1, BCL11B, and GLG1 are EWSR1-FLI1 targets, of which BCL11B and GLG1 offer a fast, simple, and cost-efficient way to diagnose Ewing sarcoma by immunohistochemistry." (PMID 29416716, 2018). "We found that when BCL11B levels are reduced by siRNAs, the transcript level of each of the genes increases in both A673 and in TC71 Ewing sarcoma cells." (PMID 23527175, 2013). "We have shown that the re-expression of the BCL11B repressed gene, SPRY1, reduces the transformation potential of Ewing sarcoma cells." (PMID 23527175, 2013). "BCL11B is a zinc finger transcription factor up-regulated by the oncogenic fusion protein EWS/FLI, creating a constitutively active transcription factor that is present in 85% of all Ewing sarcomas." (PMID 38177929, 2024).
Ewing sarcoma (continued). "Specific immunohistochemical staining of these proteins in comprehensive tissue microarrays (TMAs) combined with automated cut-off determination and combination-testing demonstrated that detecting high BCL11B and/or GLG1 levels is sufficient to reach 96% specificity for Ewing sarcoma." (PMID 29416716, 2018). "Further analyses indicated that while ATP1A1 exhibited high specificity (90%), it had no additional value for establishing Ewing sarcoma diagnosis if it was combined with BCL11B and GLG1." (PMID 29416716, 2018). "In addition to these findings in vitro, gene-set enrichment analyses of either ATP1A1-, BCL11B-, or GLG1-correlated genes within 166 primary Ewing sarcoma tumors revealed that the most significantly (min." (PMID 29416716, 2018). "The dramatic decrease in BCL11B expression levels with EWS/FLI knock-down suggests that BCL11B is not normally expressed in the Ewing sarcoma cell of origin." (PMID 23527175, 2013). "Nonetheless, this discrepancy across Ewing sarcoma cell lines suggests that inhibition of p57KIP2 is not a central feature of BCL11B function in this tumor type." (PMID 23527175, 2013). "While genes such as BCL11B and VRK1 are well characterized, others, such as IGF2BP1 and LSM6, remain poorly studied, yet they may offer valuable insights into the biology and vulnerabilities of Ewing sarcoma." (PMID 41444391, 2025). "The differing function of BCL11B in Ewing sarcoma does not appear to be due to a unique transcriptional activity in this tumor: BCL11B acts mainly as a transcriptional repressor in Ewing sarcoma, and thus acts similarly to what has been demonstrated in other cellular contexts." (PMID 23527175, 2013). "However, the microarray data have never been validated nor has the functional significance of BCL11B in Ewing sarcoma been investigated." (PMID 23527175, 2013).
craniosynostosis (10 papers, 2019 to 2024). Craniosynostosis is defined as the premature fusion of one or more cranial sutures leading to secondary distortion of skull shape resulting in skull deformities with a variable presentation. "Recently, we identified a novel BCL11B truncation variant in a patient with developmental delay, distinctive features, and early craniosynostosis." (PMID 36470856, 2022). "Although the first two reports of BCL11B alterations showed no findings of craniosynostosis, five patients have been reported to show craniosynostosis in association with BCL11B alterations, suggesting a relatively less common manifestation in humans." (PMID 36470856, 2022). "In a female patient with both CDH as well as craniosynostosis, we observed a genetic variant of the B cell leukemia 11b gene (BCL11B; OMIM 606558) resulting in an amino acid change at position 667 [p.(Gly667Glu)]." (PMID 34900871, 2021). "The phenotype of the patient with both CDH as well as craniosynostosis was similar to the phenotype of previously reported patients with BCL11B missense mutations." (PMID 34900871, 2021). "The phenotype of our patients is similar to previously reported clinical phenotypes of patients with BCL11B missense mutations, which included craniosynostosis and CDH." (PMID 34900871, 2021). "The impact of mutations in the coding sequences of Bcl11b on the development of diseases such as craniosynostosis is also presented." (PMID 33363142, 2020). "Here we describe identification of a patient with craniosynostosis carrying a de novo point mutation in BCL11B and report the generation of a mouse model that recapitulates the human phenotype." (PMID 31067316, 2019). "The clinical features of patients with BCL11B gene variants are heterogeneous, and recent studies have suggested that craniosynostosis may be associated with this gene variant." (PMID 36683525, 2023). "The description of craniosynostosis in patients with BCL11B mutations is rare." (PMID 36275064, 2022). "However, we previously discovered a de novo BCL11B missense mutation in exon 1 which encodes for [p.(Arg3Ser)] in a male patient with unilateral coronal suture craniosynostosis." (PMID 34900871, 2021). "Although a low CADD score could potentially indicate a benign variant, it is remarkable that four patients have now presented with craniosynostosis bearing a missense variant in exon 4 of BCL11B." (PMID 34900871, 2021). "This resulted in three additional BCL11B missense mutations in patients with craniosynostosis." (PMID 34900871, 2021). "Although these findings imply that both craniosynostosis as well as CDH may be associated with BCL11B mutations, further studies are required to establish whether BCL11B variants are causative mutations for both conditions or if our finding was coincidental." (PMID 34900871, 2021). "A mouse model confirmed that the de novo BCL11B missense mutation (p.Arg3Ser) in their patient could have a causative effect on the development of craniosynostosis." (PMID 34900871, 2021). "To assess the contribution of BCL11B variants to craniosynostosis aetiology more generally, we interrogated existing exome sequencing and WGS data (186 cases) and screened by targeted resequencing a panel of 382 unrelated probands, all without a genetic diagnosis." (PMID 31067316, 2019). "Although we identified several rare variants by resequencing, no plausible causative changes were identified, indicating that mutations of BCL11B leading to craniosynostosis may be rare and/or highly specific." (PMID 31067316, 2019). "Here, through comprehensive genomic analysis, a novel BCL11B truncation variant, NM_138576.4(BCL11B_v001): c.2439_2452dup [p.(His818Argfs*31)], was identified in a Japanese male patient with developmental delay, distinctive features, and early craniosynostosis." (PMID 36470856, 2022). "Therefore, it is implied that both CDH and craniosynostosis may be features associated with BCL11B missense mutations." (PMID 34900871, 2021).
craniosynostosis (continued). "The authors suggest that only a specific subset of BCL11B mutations may cause craniosynostosis." (PMID 34900871, 2021). "Further research is required to clarify the relationship between craniosynostosis and BCL11B variation." (PMID 36683525, 2023). "In this report we present the clinical reports of these four new patients with BCL11B variants and a brief review of disorders that are characterized by both CDH as well as craniosynostosis." (PMID 34900871, 2021). "We applied targeted sequencing of BCL11B in patients with craniosynostosis or with a combination of craniosynostosis and CDH." (PMID 34900871, 2021). "The BCL11B variant was thought to likely be causally significant, as Bcl11b is expressed in cranial sutures, and Bcl11b−/− mice exhibit craniofacial abnormalities, including craniosynostosis." (PMID 31067316, 2019). "We generated a mouse model for the BCL11B p.R3S substitution, and this single amino acid change recapitulated coronal suture craniosynostosis in both the heterozygous and homozygous backgrounds." (PMID 31067316, 2019). "Something similar happened in other restricted phenotypes associated with LoF mutations in BCL11B, such is craniosynostosis without other symptoms or milder features." (PMID 38472338, 2024).
developmental delay (10 papers, 2018 to 2024). "Rare missense variants of BCL11B are associated with speech impairment, developmental delay, and intellectual disability." (PMID 39693421, 2024). "Mutations of BCL11A and BCL11B, two closely related, ultra-conserved zinc-finger transcription factors, were recently reported to be associated with NDDs, including developmental delay, ASD, and ID, as well as morphogenic defects such as cerebellar hypoplasia." (PMID 38392344, 2024). "We reported a male patient with developmental delay and cerebral palsy who carried the BCL11B variant." (PMID 36683525, 2023). "Here, we report a four‐year‐ and five‐month‐old boy who presented with cerebral palsy and global developmental delay and was identified with a de novo variant in BCL11B." (PMID 36683525, 2023). "During development, BCL11B is essential for the formation and maintenance of synapses and its deficiency is associated with intellectual deficits, developmental delay and speech impairment." (PMID 36161168, 2022). "Recently, the first patient with Bcl11b/Ctip2 mutations was examined revealing an overall developmental delay with speech impairment and intellectual disabilities." (PMID 29674952, 2018). "Recently, mutations in BCL11A and BCL11B, two ultra-conserved zinc-finger transcription factors, have been associated with multiple cases of neurodevelopmental disorders, including developmental delay, autism spectrum disorder, intellectual disability, and structural brain alterations." (PMID 38392344, 2024).
Immunodeficiency (10 papers, 2018 to 2025). Failure of the immune system to protect the body adequately from infection, due to the absence or insufficiency of some component process or substance. "In humans, heterozygous mutations in BCL11B have been linked to intellectual disability and varying degrees of immunodeficiency." (PMID 40771806, 2025). "Understanding the precise mechanisms underlying BCL11B’s regulation of lineage specification will provide critical insights into both normal hematopoiesis and immune dysfunctions associated with BCL11B mutations." (PMID 40771806, 2025). "Although the immune system is affected in 74% of individuals carrying BCL11B variants, only a few develop severe immunodeficiency." (PMID 38392344, 2024). "In contrast to LOF variants of BCL11B, patients with severe immunodeficiency typically harbor missense mutations in their genome, suggesting dominant-negative and/or gain-of-function mechanisms to be involved in the pathogenesis of disease." (PMID 38392344, 2024). "Variants of BCL11B have been found in patients with neurodevelopmental disorders and immunodeficiency." (PMID 36683525, 2023). "BCL11B-related disorder is an intellectual development disorders characterized by malformation, speech delay, and T-cell abnormalities or immune deficiency." (PMID 36176959, 2022). "Those patients carrying the pathogenic variations of the BCL11B gene tend to have immune deficiency or intellectual developmental disorder, the major clinical manifestions are speech delay, dysmorphic facies, and T-Cell abnormalities." (PMID 36176959, 2022). "According to a recent report, the mutation of transcription factor gene BCL11B is associated with the development of neurodevelopmental disorders and immune deficiency." (PMID 36176959, 2022). "Most of these patients presented with neurodevelopmental disorders and immunodeficiency with reduced type 2 innate lymphoid cell and were carriers of loss of function mutations in BCL11B." (PMID 34900871, 2021). "De novo mutations of BCL11B have been associated with neurodevelopmental disorder and immunodeficiency, such as immunodeficiency 49 (IMD49) and intellectual developmental disorder with speech delay, dysmorphic facies, and T-cell abnormalities (IDDSFTA)." (PMID 33194885, 2020). "Additional genetic defects in MTHFD1, RMRP, CORO1A, PNP, DOCK8, ATM, and BCL11B, among others also cause combined immunodeficiencies, which can be detected by low TREC copy number analysis." (PMID 29713328, 2018). "First, a case report described a male patient with a heterozygous de novo missense BCL11B mutation (p.Asn441Lys), who presented with severe combined immunodeficiency as well as neurological, dermal and facial dysmorphisms including hypertelorism, short palpebral fissures and micrognathia." (PMID 34900871, 2021). "Given a lack of definitive immune deficiency diagnosis, it is necessary to reveal the impact of BCL11B gene variation on the immune system through more clinical cases and pathogenic mechanism studies." (PMID 36176959, 2022).